MET (MET proto-oncogene, receptor tyrosine kinase)
Diseases named in the same sentence as MET in open-access papers (continued):
Sharing a sentence is not in itself a finding about the gene and the disease.
cancer (continued). "MET is a member of the receptor tyrosine kinase family, which amplifies frequently in various human cancers." (PMID 31349699, 2019). "Taken together, Trousseau’s syndrome is well recognized as thrombotic disorders that are not only due to cancer-derived mucin or TF, but also to other thrombogenic mechanisms, such as tumor hypoxia and MET gene activation." (PMID 30959839, 2019). "Moreover, the validation of MET as a potent driver in BRCA1-associated tumorigenesis underscores the potential of iterative analysis of CNAs in progressively complex mouse models as an approach for identifying putative cancer genes that promote tumorigenesis in specific genetic contexts." (PMID 30674894, 2019). "This is the first conceptual link between nuclear RTK/MET kinases to cancer evolution and clinical investigation including cancer stem-like cells in drug adaption and resistant survival which fits the Darwin theory." (PMID 30700325, 2019). "All WB1P-Met tumors were classified as poorly differentiated ER/PR-negative ductal carcinomas and showed MET overexpression and active MET signaling." (PMID 30674894, 2019). "The MET overexpression and activation play a crucial role in cancer cell proliferation, migration, invasion, and metastasis." (PMID 30083132, 2018). "Owing to its importance in cancer progression, aberrant c-Met signalling has been studied specifically in the context of HNSCC mainly by identifying MET gene mutations and copy number alterations or by assessing c-Met overexpression." (PMID 29991692, 2018). "Several case studies of cancer patients with MET exon 14 skipping or MET amplification who progressed on crizotinib treatment had either pre-existing or acquired secondary point mutation(s) in the MET kinase domain." (PMID 29188469, 2018). "Of the 82 unique prognostic biomarkers identified, meta-analyses showed prominent biomarkers, including COX-2, PAK-1, p14ARF, PD-L1, MET, LC3B, IGFBP7 and LGR5, associated to each hallmark of cancer." (PMID 30185893, 2018). "To prove that cigarette smoke renders NSCLC cancer cells more resistant to EGFR TKI through induction of c‐MET signaling, we first confirmed the c‐MET activation in H292/B[α]P cells by western blot analysis." (PMID 29570930, 2018). "MET and HGF co-targeting has been previously investigated in MET-addicted tumors and in cancers expressing a MET/HGF autocrine loop." (PMID 30544501, 2018). "Third, LINE-1 hypomethylation activates oncogenes (e.g., c-MET) and cell cycle-related genes (e.g., CDK6), which are associated with cancer progression." (PMID 29755690, 2018). "As a transcriptional activator, MACC1 directly regulates the transcription of numerous genes involved in EMT, metastasis, cancer stemness, and drug resistance, including MET, SPON2, and MDR1/ABCB115–18." (PMID 30082743, 2018). "In this respect, it is worth mentioning that c-MET availability has also been correlated with resistance to radio- and chemotherapy in different cancer types." (PMID 30159127, 2018). "Tivantinib ARQ197, a non-ATP competitive selective small-molecular inhibitor, not only targets c-MET, but also targets cyclin B1, the proteasome, and glycogen synthase kinase 3 in cancer." (PMID 30360560, 2018). "Cancer cells containing MET gene amplification were highly dependent on c-Met signaling for both proliferation and cell survival." (PMID 30134579, 2018). "As MET activation is shown to drive cancer initiation, progression, and resistance to chemotherapeutics, targeting MET signaling has become a promising strategy for cancer treatment." (PMID 30208970, 2018). "Several microRNAs, including miR‐613, miR‐138, miR‐206, miR‐185 and miR‐101, have been demonstrated to target c‐MET for cancer proliferation and progression." (PMID 29570930, 2018). "Dysregulation of the MET signaling pathway has been reported to occur in a variety of cancers, with correlations to poor clinical outcomes and drug resistance." (PMID 29433585, 2018).
cancer (continued). "Migrating cancer cells seem to evade anoikis by MET-dependent upregulation of the cytoskeleton adhesion receptors, which allows them to interact with the new surrounding cells and to elude apoptosis." (PMID 30544501, 2018). "HGF/MET signalling has been repeatedly reported to be a critical pathway for communication between stroma and cancer cells." (PMID 29993037, 2018). "The results revealed ligand-mediated activation of alternative RTK expressed on TKI-naïve cancer cells that functioned as bypass pathways to MET and FGFR-specific TKIs." (PMID 29458371, 2018). "Migliore and colleagues support the idea of post‐transcriptional regulation of MET by showing that also miR‐34b, miR‐34c, and miR‐199a‐5p negatively regulate MET expression and thereby inhibit invasive growth in different cancer cell lines." (PMID 30004628, 2018). "MiRNA profiling combined with RNA‐Seq in MET‐addicted cancer cell lines led us to identify the miR‐205/ERRFI1 (ERBB receptor feedback inhibitor‐1) axis as a novel mediator of resistance to MET tyrosine kinase inhibitors (TKIs)." (PMID 30021798, 2018). "While MET inhibitors are in clinical trials against several cancer types, the clinical efficacies are controversial and the molecular mechanisms toward sensitivity remain elusive." (PMID 30208970, 2018). "In this model, the combination of MvDN30 and decoyMETK842E targeted directly human cancer cells, strongly impairing MET phosphorylation in primary tumors, and affecting the stromal component of primary tumors." (PMID 30544501, 2018). "Previous work, along with pre‐clinical and clinical data presented herein, supports the view that EGFR activation can in turn substitute for MET signaling in MET‐driven cancer cells." (PMID 30021798, 2018). "This review focuses on understanding how the ECM can influence the HGF/c-MET signaling pathway during cancer progression." (PMID 30352967, 2018). "Both c-MYC and MET are proto-oncogenes related to several cancer hallmarks, like sustaining proliferative signaling, evading growth suppressors, enabling replicative immortality and activating invasion and metastasis." (PMID 30143666, 2018). "Oncogenic membrane receptor tyrosine kinases such as MET and EGFR, or auto-active variants thereof, are important targets for cancer precision therapy." (PMID 29728634, 2018). "Hepatocyte growth factor (HGF) plays an important role in cancer progression via phosphorylation of MET (c-met proto-oncogene product, receptor of HGF)." (PMID 30469509, 2018). "The critical role of crosstalk between the c‐MET and ErbB family in the development of resistance to cancer therapeutics has been well elucidated." (PMID 29570930, 2018). "Due to its oncogenic features, several MET inhibitors have been used to treat cancers in clinical trials." (PMID 30126419, 2018). "Although few in vivo studies have been reported on these thus far, literature describes various interesting cancer targets for OC, being the main phenylethanoid studied for both the c-MET and hepatocyte growth factor (HGF)." (PMID 30250008, 2018). "In the vast majority of tumors, wild-type MET behaves as a ‘stress-response’ gene, and relies on ligand stimulation to sustain cancer cell ‘scattering’, invasion, and protection form apoptosis." (PMID 30544501, 2018). "Mounting evidence supports the notion that c-MET inhibitors play significant roles in human cancers, including CRC." (PMID 30360560, 2018). "The same MET/HGF-dependent mechanism described in a physiological context is exploited by cancer cells to disseminate from the tissue of origin and to colonize a different organ." (PMID 30544501, 2018). "Despite advances and improvement in techniques to antagonize HGF/c-MET pathway using small molecule inhibitors, many cancers are unresponsive to these inhibitors due to resistance in clinical research." (PMID 30360560, 2018).
cancer (continued). "Since regulation of MET in RMS is largely unexplored and reports indicate that SPRY2 can alter MET signaling in cancers, we carefully analyzed MET, SPRY2 and their role in RMS, using representative RMS cell lines." (PMID 29445192, 2018). "In this context, cancer cells depend on MET signaling for their growth and survival, a phenomenon that is common to other tyrosine kinase receptors and that has been indicated as ‘oncogene addiction’." (PMID 30544501, 2018). "Crizotinib was used as a comparator, as most of the case reports of cancer patients with MET exon 14 skipping treated with MET kinase inhibitor were with crizotinib." (PMID 29188469, 2018). "MACC1 functions as a key regulator of the HGF/c-MET axis, which is a promising target for cancer therapy." (PMID 29510730, 2018). "The malignant behavior of cancer cells is nurtured by the collateral pro-angiogenic activity of the MET/HGF axis in endothelial (ECs) and stromal cells." (PMID 30544501, 2018). "Of the 82 unique prognostic biomarkers identified, meta-analyses showed several promising biomarkers, including COX-2, PAK-1, p14ARF, PD-L1, MET, LC3B and LGR5, associated to each hallmark of cancer feature." (PMID 30185893, 2018). "Dysregulated pro-HGF activation (with upregulated MET phosphorylation) is reported to promote cancer progression in various cancers." (PMID 30469509, 2018). "Similar to the clinical situation of HCC treatment, most of the c-MET inhibitors have limited benefit for treatment of cancer because of adverse events and c-MET-positive limitation." (PMID 30360560, 2018). "In anticancer drug resistant small-cell lung cancer cells, c-MET expression was high and treatment with a c-MET-specific inhibitor SU11274 (SU112) sensitized cancer cells to cisplatin and paclitaxel." (PMID 29291022, 2017). "For example, the role of c-MET as a biomarker in fluorescence imaging seems to be cancer type-specific." (PMID 28915633, 2017). "We therefore evaluated the effect of BsAb on c-MET-mediated signaling in the regulation of cancer cell death." (PMID 28404966, 2017). "These indicate that BCRP elevation is one of molecular mechanisms of c-MET/EGFR-induced cancer resistance." (PMID 29291022, 2017). "BsAb strongly downregulated c-MET protein expression in both dose- and time-dependent manners in the two cancer cell lines." (PMID 28404966, 2017). "Levels of p-AKT and p-ERK1/2 were also repressed in the shNRF2-SKOV3, which indicates lowered c-MET/EGFR downstream signaling in NRF2-silenced cancer cells." (PMID 29291022, 2017). "Activation of the HGF/c-MET axis in cancer has been reported to be involved in cellular proliferation, survival, migration and angiogenesis." (PMID 28511645, 2017). "One of these signaling modules, HGF-c-MET, is frequently overexpressed in AVPCa and AR inhibitor treated cancers." (PMID 28103576, 2017). "Aberrant activation of HGF/c-MET signalling by mutation, autocrine or paracrine HGF stimulation, or overexpression has been implicated in the oncogenesis of large number of cancers." (PMID 28511645, 2017). "Hepatocyte growth factor receptor (HGFR) or c-MET is encoded by the MET gene and it is a RTC associated with enhanced migration, invasion and angiogenesis when overexpressed in cancer." (PMID 31093353, 2017). "As MET signaling has been reported to be pivotal in development of cancer and metastasis we created another TMA including tissue of 18 primary ccRCCs and corresponding metastasis." (PMID 27894094, 2017). "Cancer cells exposed to hPSC secretions exhibited increased activation/phosphorylation of c-MET most likely in response to HGF in the secretions." (PMID 29100344, 2017). "HGF is an example of a molecule involved in this kind of interaction, wherein cancer cells stimulate fibroblasts to produce HGF that in turn transduces signals through its specific receptor tyrosine kinase MET." (PMID 29202869, 2017).
cancer (continued). "First, we evaluated c-MET and PD-L1 mRNA expression in eight human cancer cell lines using real-time quantitative polymerase chain reaction (qPCR)." (PMID 28404966, 2017). "Some genetic alterations, including changes in EGFR and MET, were observed at relatively low frequencies, and these alterations were detected in less than 5% of cancers analysed in our study." (PMID 28764718, 2017). "c-MET/EGFR signaling is a strong stimulator for cancer proliferation and survival, and therefore, the miR-206-mediated dual repression of c-MET and EGFR can confer antitumor effects." (PMID 29291022, 2017). "It was discovered that ATP-binding cassette subfamily B member 1 (ABCB1) overexpression, which was associated with cancer stem cell (CSC) properties and EMT, was involved in the acquired resistance to MET inhibitors." (PMID 27757846, 2017). "Studies suggest that c-MET activation is a potential mechanism of resistance not only to MEK1/2 inhibitors but also to ADAM17 inhibitors in certain types of cancer." (PMID 29230082, 2017). "We report here that Poloppin and Poloppin-II, compounds that target the protein-protein interactions of human Polo-like kinases, suppress the growth of KRAS-mutant cancer cells as single agents, or in combination with c-MET inhibitors." (PMID 28807782, 2017). "c-MET-targeted therapies have been tested in preclinical models and patients, with significant benefits for cancer treatment." (PMID 28485003, 2017). "Binding of HGF to its receptor, MET, leads to receptor dimerization and induction of signaling pathways that support growth, survival, motility and metastatic spread of cancer cells." (PMID 28420162, 2017). "The established relevance of SF/HGF-MET in tumorigenesis and progression suggests that MET inhibition is a potential strategy in cancer therapy, a notion supported by a growing body of preclinical evidence." (PMID 28532501, 2017). "At the same time, analysis of the effect of BsAb on c-MET protein levels suggests that BsAb can induce protein degradation, in both dose- and time-dependent manners, in cancer cells (including MKN45 and A549 cells)." (PMID 28404966, 2017). "Supporting these results, are our in vitro observations whereby HGF inhibition or c-MET blockade alone inhibited cancer cell proliferation." (PMID 29100344, 2017). "The top five up-regulated cancer stemness associated genes include: SNAI2 (SLUG) (8.2 folds), SOX9 (6.4 folds), ITGB3 (integrin β3) (5.4 folds), CD44 (4.3 folds) and MET (2.9 folds) (DU145FP vs. DU145WT)." (PMID 28698547, 2017). "HGF/SF, the ligand of HGF receptor MET, is involved in PCa progression stimulating proliferation and migration of cancer cells as well as prostate fibroblasts and CAFs." (PMID 28510269, 2017). "c-MET is an attractive drug target in cancer therapy, and various targeted drugs have been used in multiple clinical trials as cancer therapeutic agents." (PMID 28485003, 2017). "Binding of HGF to its receptor c-MET on cancer cells stimulates several intracellular signalling cascades, which regulate cancer cell functions such as proliferation, migration and apoptosis." (PMID 29100344, 2017). "HGF-induced MET activation also triggers multiple pro-survival pathways in cancer cells, such as AKT and STAT3, promotes epithelial-mesenchymal transition (EMT), and thus confers primary and acquired resistance to anti-cancer therapy." (PMID 28420162, 2017). "This hPSC-induced cancer cell proliferation was unchanged by exposure of cells to hPSC secretions pre-treated with AMG102 or when cancer cells were treated with c-MET inhibitor alone." (PMID 29100344, 2017). "The results showed that genes co-amplified with MET or ERBB2 also show high amplification frequency in cancers other than GC." (PMID 29190909, 2017). "We showed that a novel inhibitor of pro-HGF activation, SRI31215, blocks the crosstalk between cancer cells and fibroblasts and overcomes resistance to anti-MET therapy in MET-amplified NSCLC cells." (PMID 28968967, 2017).
cancer (continued). "Here, we report the isolation of a new human, phage-derived monoclonal antibody to MET (107_A07) displaying potent receptor antagonistic activity, and we describe the activity of 107_A07 on cancer cells in vitro and in in vivo." (PMID 28827556, 2017). "Aberrant activation of EGFR, HER2, c-MYC, or MET is considered to be a promising target for specific molecular treatments in various cancers, including CRC." (PMID 28764718, 2017). "The results showed that all eight cancer cell lines also expressed c-MET protein at a relative high levels." (PMID 28404966, 2017). "In preclinical studies cancer cells rapidly develop resistance to MET kinase inhibitors, which will probably translate to resistance in patients." (PMID 28968967, 2017). "In conclusion, BsAb treatment strongly inhibited the growth of cancer cells in vitro and in vivo, more effectively than PD-1 antibody or simulated one-armed c-MET antibody." (PMID 28404966, 2017). "Binding of HGF to its transmembrane cell surface receptor c-MET, which is expressed on cancer cells activates several intracellular cell-signalling pathways that play a pivotal role in cancer cell proliferation and migration." (PMID 29100344, 2017). "Immunoblotting showed increased phosphorylated c-MET as well as total c-MET in cancer cells exposed to hPSC secretions for 10 minutes." (PMID 29100344, 2017). "It has been demonstrated that in cancer cells, activation of hepatocyte growth factor receptor (HGFR, also known as MET), human epidermal growth factor receptor 2 (HER2, also known as ERBB2), and tyrosine kinases stimulates cortactin phosphorylation." (PMID 29152154, 2017). "Supporting this notion, it has been shown that HGF is required for optimal activation of the MET kinase in MET amplified cancer cells." (PMID 28420162, 2017). "TCGA data analysis of various cancer types showed that genes co-amplified with MET or ERBB2 had high amplification frequencies in other cancers." (PMID 29190909, 2017). "All cell types were negative for haematopoietic cell markers CD45, CD34, CD19, CD14, human lymphocyte antigen-DR (HLA-DR), the carcinoma cell marker (c-MET) and EPCAM." (PMID 28419140, 2017). "The expression of HGF and c-MET was also checked in GC liver metastases and para-carcinoma tissues, and HGF is highly expressed in liver tissues but not in the metastases." (PMID 28393839, 2017). "Plasma extracted from 171 patients with a variety of cancers was analyzed for ctDNA (54 genes and copy number variants (CNVs) in three genes (EGFR, ERBB2 and MET))." (PMID 26848768, 2016). "Many studies have reported that MET is overexpressed in a variety of human cancers including liver, lung, breast, and colon cancer." (PMID 27813498, 2016). "Collectively, these results demonstrate that ABT-700 can inhibit the proliferation and consequently induce apoptotic cell death in cancer cells addicted to c-Met signaling driven by MET amplification." (PMID 26879245, 2016). "Future studies will have to address the role of CD44 and RHAMM for radiosensitivity of cancer cells, possibly also including further binding partners of both proteins, such as MET." (PMID 26870892, 2016). "c-Cbl downregulates multiple RTKs including EGFR, MET, and others, which in turn regulate Wnt signaling in different cancer types (RTK-Wnt crosstalk)." (PMID 27661103, 2016). "A MET FISH assay was developed for detecting MET gene amplification in human biopsied cancer tissues utilizing a probe that spans 456 k-bases encompassing the entire MET gene located on the chromosome locus 7q31.2." (PMID 26879245, 2016).